MICA (MHC class I polypeptide-related sequence A)
Diseases named in the same sentence as MICA in open-access papers (continued):
Sharing a sentence is not in itself a finding about the gene and the disease.
tumor (continued). "Sub-lethal doses of radiation can induce immunogenic modulation in tumor cells via enhancing the expression of NK cell activating ligands such as MICA/B and ULBP1-3, thereby enhancing NK-mediated killing." (PMID 40710340, 2025). "In a prevention model, immunized mice showed a clear delay in tumor growth after being injected with MICA-positive tumor cells." (PMID 41301424, 2025). "Conversely, tumor cells can evade immune detection through mechanisms that involve the shedding of NKG2DLs, such as MICA/B." (PMID 40013140, 2025). "A high expression of MICA or other ligands on the surface of tumor cells can be regarded as an immune checkpoint." (PMID 40563539, 2025). "Studies have shown that tumor cells actively release MICA into the TME through proteolytic shedding and exosome‐mediated secretion, which in turn weakens NK cell‐mediated cytotoxic responses." (PMID 40959206, 2025). "As tumors progress, tumor cells develop various strategies to reduce surface MICA/MICB expression and impair NKG2D–NKG2DL interactions, ultimately leading to immune escape." (PMID 40959206, 2025). "Recent studies have shown that stress and damage induced by nCRT combined with a PD-L1 inhibitor in tumor cells can upregulate stress ligands (such as MICA/B) on the surface of tumor cells, thereby enhancing NK cell recognition and killing ability." (PMID 40936903, 2025). "An in vitro co‐culture of MM and NK cells assessed the effects of SMI‐16a (PIM‐2 inhibitor) and ABT888 (PARP1 inhibitor) on tumor proliferation and apoptosis, focusing on DNA damage, MICA expression, and NK cell functionality." (PMID 40557764, 2025). "The highly polymorphic human major histocompatibility complex class I chain-related gene A (MICA) regulates immune surveillance and destroys tumor cells by activating its receptor, the natural killer group 2D." (PMID 41431073, 2025). "NK cells exert their cytotoxic effects primarily through activating receptors, such as NKG2D, which recognizes stress-induced ligands on the surface of tumor cells, such as MICA, MICB, and ULBPs." (PMID 40076725, 2025). "When normal cells (especially those derived from epithelial tissues) undergo tumor transformation, the expression levels of MICA and other ligands increase significantly, attracting NK cells and binding to the NKG2D receptor." (PMID 40563539, 2025). "The expression of MICA/B markers was comparable in both tumor cells lines, highlighting the supplementary role provided by non-specific activation." (PMID 40002679, 2025). "Malignant tumors of epithelial origin usually highly express NKG2D ligands such as MICA, which can attract NK cells to kill tumor cells and also serve as an important basis for NK cell-based immunotherapy." (PMID 40563539, 2025). "Meanwhile, NKG2D on exosomes facilitates tumor cell targeting by recognizing stress-induced ligands such as MICA, MICB, and ULBP, which are commonly overexpressed in tumors." (PMID 40076725, 2025). "For example, an antibody that blocks the shedding of MICA/B from tumor cells and induces ADCC and antibody-dependent cellular phagocytosis has shown early signs of clinical activity in patients with advanced solid tumors." (PMID 40116579, 2025). "Tumor antigens are in turn targeted via binding to either MICA via NKG2Drp or EGFR via EGFR scfv or epidermal growth factor (EGF) ligand." (PMID 40741595, 2025). "We review the effects of MICA amino acid polymorphism on the affinity of the NKG2D signal pathway and analyze in detail the specific role of MICA amino acid polymorphism in tumor immunity." (PMID 41594588, 2025). "For example, the PROS1-AXL pathway mediates the interaction between MICA+ tumor cells and MMP9+ macrophages, to facilitate tumor immune escape in advanced HCC." (PMID 39981249, 2025). "Tumor invasion depth, KRAS or driver gene mutations were associated with patients carrying the MICA-129 Met/Met genotype." (PMID 41431073, 2025).
tumor (continued). "These systems selectively interacted with MICA/B-expressing tumor cells, minimizing off-target effects." (PMID 40917849, 2025). "Elevated levels of secreted MICA/B bind to the natural killer group 2D receptor on NK cells and promotes endocytosis of the receptor, decreasing NK cell ability to bind and recognize MICA/B on tumor cells." (PMID 40429950, 2025). "For instance, proteolytic shedding of MICB from the tumor cell surface can reduce detectable levels, as tumor cells often shed MICA/B proteins to evade immune detection." (PMID 40670925, 2025). "Secreted BICA generated an effective immune response and reduced tumor growth in epidermal growth factor receptor (EGFR)/major histocompatibility complex-related chain A (MICA)-positive tumors in vitro." (PMID 40741595, 2025). "MICA is mainly expressed on the surface of tumor cells derived from epithelial cells, and digestive system malignancies are the main types of tumors derived from epithelial cells." (PMID 40563539, 2025). "The presence of CAFs within the model induced alterations in the expression levels of MICA/B and PD-L1 by tumor cells within the 3D-2 model." (PMID 40710292, 2025). "These soluble ligands, when binding to NKG2D, cannot activate NK cells and also block the binding of NKG2D to MICA on the surface of tumor cells, enabling tumor cells to evade the killing effect of NK cells." (PMID 40563539, 2025). "Design suppressor drugs targeting tRF-3021a to down-regulate the expression of ADAM10 protein, maintain the expression of membrane protein MICA, reduce soluble MICA, and remove the immune escape of tumor cells to NK cells." (PMID 40726981, 2025). "Metalloproteinases hydrolyze MICA and MICB on the surface of tumor cells to generate soluble MICA and MICB (sMICA and sMICB)." (PMID 40563539, 2025). "The class 1 HDAC inhibitor, entinostat, has been shown to upregulate MHC-I in NB, resulting in the enhanced cytotoxicity of tumor-specific T cells, and it also increased the expression of MICA/MICB, augmenting NK recognition of tumor cells as well." (PMID 40507292, 2025). "This combination induces DNA damage in MM cells and augments the tumor‐killing function of NK cells via the NKG2D/MICA signaling axis." (PMID 40557764, 2025). "The S-palmitoylation status of MICA is crucial for tumor immunotherapy, and comprehensive research in this area is anticipated to yield novel approaches and targets for advancing future immunotherapeutic strategies." (PMID 40066091, 2025). "This inability in separating the abundances of activating ligands can be associated with the inability of NK cells to respond to infected or tumor target cells expressing higher abundances of activating ligands such as ULBP1–6 or MICA/B." (PMID 40196617, 2025). "Tumor‐induced shedding of the stress ligand MICA/B blocks NKG2D‐mediated tumor recognition, further restricting NK cell function." (PMID 41143064, 2025). "To confirm the role of MICA in tumor cells in inducing M2-like polarization through the PPAR-α/EHHADH pathway, we employed a co-culture model consisting of MICA+HCC cells and macrophages." (PMID 40723248, 2025). "Growing body of evidence suggested that the proteolytic release of MICA/B from the plasma membrane is a focal mechanism for the evasion of the tumor cells from lysis by NKG2D-expressing immune cells." (PMID 40108523, 2025). "These targets were selected to represent diverse tumor scenarios, with varying expression of surface CAR target antigens (i.e., CD70) and NKR ligands (e.g., MICA/B, ULBPs, CD112, and CD155), thus modeling RCC-associated tumor heterogeneity." (PMID 40885188, 2025). "For example, targeting BET (a tumor cell biomarker) with bromodomain inhibitors can enhance MICA expression on tumor cells, thereby improving NK cell recognition and tumor cell killing." (PMID 39859231, 2025).
tumor (continued). "Contrary to mouse cells, human NK cell-mediated killing did not correlate with surface expression of MHC class I molecules on tumor cells but correlated with NKG2D ligands MHC class I polypeptide-related sequence A/B (MICA/B)." (PMID 39889712, 2025). "The binding of MICA on tumor cells to NKG2D on NK cells is a key step in triggering ADCC by NK cells." (PMID 41301424, 2025). "So far, the successful generation and effect of therapeutic antibodies inhibiting the shedding of MICA/B, thereby promoting NK cell-driven tumor immunity, has been described." (PMID 41050431, 2025). "NK cells recognize tumor cell surface stress molecules (such as MICA/B) via NKG2D receptors, releasing perforin and granzyme to mediate tumor inhibition." (PMID 40433371, 2025). "During tumor immunosurveillance, the expression of MICA, MICB, and ULBP on tumor cells can be recognized by NKG2D, a NK-like activating receptor (NKR) expressed on γδT cells, particularly in Vγ9Vδ2 subset." (PMID 40226616, 2025). "In NB, senescent tumor cells overexpress the lncRNA MALAT1, which regulates the expression of ADAM10 metalloproteinase and the consequent release from tumor cells of the NKG2D ligand MICA/B." (PMID 40496868, 2025). "MICA-gene-specific transcriptional activation and overexpression by tumor cells using CRISPR/Cas9 technology were studied by Sekiba and colleagues and resulted in increased NKG2D-mediated clearance of the targeted cells in vitro." (PMID 39339180, 2024). "MHC class I chain-related polypeptide A (MICA) expression is upregulated by many tumor cell lines and primary tumors and serves as a ligand for the activating NK group 2D (NKG2D) receptor on NK cells and subpopulations of T cells." (PMID 38180524, 2024). "Subsequently, experiments validated that DNA damage not only induced MICA expression in tumor cells via IRF1, but also upregulated PROS1 levels in HCC cells, stimulating macrophages to secrete MMP9." (PMID 38254761, 2024). "Tumor cells can evade immune detection by shedding MICA/B via proteolytic cleavage at the α3 domain of MICA/B." (PMID 39796666, 2024). "Next, we employed CellChat to conduct pathway-based analyses of ligand-receptor (L-R) interactions between MICA+/MICA− tumor cells and MMP9+/MMP9− macrophages." (PMID 38254761, 2024). "In our previous investigation, we observed that DNA damage-induced upregulation of MICA expression resulted in the activation of NKG2D-mediated anti-tumor immune responses by NK cells and CD8+ T cells." (PMID 38254761, 2024). "MICA-expressing virus shows improved tumor growth control capacity compared to the parental virus throughout the study, although the difference was not significant." (PMID 38180524, 2024). "The interaction between MICA+ tumor cells and MMP9+ macrophages was mediated through the PROS1-AXL pathway." (PMID 38254761, 2024). "In this study, expression levels of MMP9 and MICA were significantly elevated in macrophages and tumor cells, respectively." (PMID 38254761, 2024). "The recruited NK cells and CD8+T cells become activated by binding to MICA/B on the surface of tumor cells, exerting the tumor killing effect of the immune system." (PMID 38882209, 2024). "In tumor cells, ligands of ULBP1, ULBP2/5/6, ULBP3, ULBP4, and MICA/B can bind to NKG2D receptors among tumor-activating receptors of NK cells." (PMID 39339179, 2024). "Proteolytic proteases‐mediated tumor‐shedding of sMICA/B accounted for one of the major mechanisms for MICA/B tumor evasion of NKG2D immune surveillance." (PMID 38882209, 2024). "Other studies have shown that histone deacetylases (HDACs) inhibitors can induce higher levels of MICA/MICB expression on tumor cells, thus promoting NK cell tumor activity." (PMID 39339180, 2024). "TGF-β production increases during tumor growth and malignant progression, and selectively suppresses the expression of MICA, ULBP2, and ULBP4, while MICB, ULBP1, and ULBP3 are unaffected." (PMID 38245520, 2024).
tumor (continued). "Higher levels of MMP‐9 mRNA and protein have been observed in PAs compared to healthy tissues, where it facilitates the cleavage of MICA into soluble MICA, ultimately promoting tumor immune escape." (PMID 39688352, 2024). "Through this analysis, we elucidated the interactions between MICA+ tumor cells and MMP9+ macrophages, primarily mediated via the PROS1-AXL axis in advanced HCC." (PMID 38254761, 2024). "In this study, we established a soluble MICA-induced NK cell desensitization model to provide insights into the challenges posed by soluble MICA in the serum of clinical tumor patients and its adverse prognostic implications." (PMID 39048814, 2024). "Tumor cells can downregulate surface expression of MICA through shedding, mediated by proteolytic cleavage at the α3 domain." (PMID 38550583, 2024). "Among them, NKG2D ligands MICA/B are upregulated in many types of human tumor cells due to cellular stress such as DNA damage and then activate NK cells for immune surveillance." (PMID 38882209, 2024). "This downregulation is considered an anti-tumor escape mechanism, with MHC class I polypeptide-related sequence A (MICA) showing the most significant decrease." (PMID 38983267, 2024). "This highlighted that MMP9 secretion subsequently facilitated the proteolysis of MICA, thereby promoting the evasion of the tumor from immune surveillance." (PMID 38254761, 2024). "MICA+ tumor cells stimulated the secretion of MMP9 from macrophages through the PROS1-AXL axis, thereby facilitating the proteolytic shedding of MICA into soluble MICA." (PMID 38254761, 2024). "We demonstrated that viral-mediated mutant MICA expression activates NK cells ex vivo and in mouse tumor models, and that such activation mediates improved antitumor efficacy." (PMID 38180524, 2024). "Activation of the interferon gamma (IFN-γ) signaling pathway was observed in MICA+ tumor cells and MMP9+ macrophages." (PMID 38254761, 2024). "NK cells have multiple activating receptors to detect stress-induced ligands that are upregulated on tumour cells, such as MICA/B and ecto-calreticulin, and can therefore mediate killing in the absence of a specific tumour neoantigen." (PMID 38223411, 2024). "Essentially, NK-cell cytotoxicity is enhanced after mild HT (<40 °C), which causes the clustering of NKG2D stimulatory receptors on the NK-cell surface and an increased expression of the stimulatory ligands, HSP70 and MICA, on the tumor cell surface." (PMID 39518094, 2024). "Subsequently, experimental validation confirmed that MICA+ tumor cells upregulated MMP9 expression in macrophages through the PROS1-AXL axis." (PMID 38254761, 2024). "The increased MMP9 activity resulted in the proteolytic shedding of MICA, leading to the release of soluble MICA (sMICA) and the subsequent facilitation of tumor immune escape." (PMID 38254761, 2024). "We show increased cytotoxicity of MICA+ tumor cells compared to WT tumor cells in vitro, with efficacy comparable to that of free drug but with much higher specificity for MICA+ cells." (PMID 38550583, 2024). "Specifically, we explored the potential interaction between MICA+ tumor cells and MMP9+ macrophages." (PMID 38254761, 2024). "As MICA/B expressing tumor cells are more sensitive to NK cytotoxicity, many epigenetic drugs are found to increase MICA and MICB expression and exert antitumor effects." (PMID 38882209, 2024). "For example, a large number of tumors overexpress ADAM proteases to shed MICA (MHC class I polypeptide-related sequence A) out of the cell membrane of tumor cells." (PMID 38180524, 2024). "Proteolytic shedding of MICA and MICB caused by tumor evasion promotes tumor progression, which is usually alleviated by antibody-mediated inhibition to restore the NK-driven innate immunity." (PMID 38673829, 2024).
tumor (continued). "We employed scRNA-seq analyses to investigate the communication between MICA+ tumor cells and MMP9+ macrophages via the PROS1-AXL axis and revealed an upregulation of the IFN-γ signaling pathway in MICA+ tumor cells." (PMID 38254761, 2024). "Particularly, natural killer group 2, member D (NKG2D) receptor on NK cells recognizes stress‐induced ligands—the MHC class I chain‐related molecules A and B (MICA/B) presented on tumor cells and is key to trigger the cytolytic response of NK cells." (PMID 38882209, 2024). "The MICA/B-NKG2D signal axis plays a pivotal role in tumor immune surveillance, with MICA being a critical ligand for NKG2D and widely expressed in various tumor cells." (PMID 39048814, 2024). "Other HDAC inhibitors have been shown to increase the expression of stress-inducing ligands, such as MICA, MICB and ULB-3, on the surface of tumor cells, thereby increasing the susceptibility of these tumor cells to NK cell-mediated cytolysis." (PMID 38254784, 2024). "MICA, which is overexpressed on the surface of tumor cells due to genotoxic stress, is a major activator of NK cells by binding to the NKG2D receptor." (PMID 38180524, 2024). "We identified the existence of an interaction between MICA+ tumor cells and MMP9+ macrophages mediated via the PROS1-AXL axis." (PMID 38254761, 2024). "To investigate the interplay between MICA+ tumor cells and MMP9+ macrophages, we employed CellChat, a computational tool, to unravel the intricate cell-cell communication and predict significant biological insights from scRNA-seq data." (PMID 38254761, 2024). "In cervical cancer, improved prognosis was linked to the expression of MICA/B and ULBP1, whereas reduced survival (univariate analysis only) was seen when tumours were RAET1E (ULBP4)- or RAET1G (ULBP5)-positive." (PMID 37626965, 2023). "Another way to increase the NKG2D mediated anti-tumor effect of γδ T cells, is to use recombinant immunoligands consisting of a CD20 single-chain fragment variable (scFv) linked to MICA or ULBP2." (PMID 37426670, 2023). "Meanwhile, IHC staining for MICA expression decreased in the tumor compared to the background liver." (PMID 36765808, 2023). "In order to evade NKG2D mediated recognition, tumour cells shed MICA from their surface, and this shedding from melanoma cells is achieved with exosomes." (PMID 37022605, 2023). "Apart from TCR ligands, ligands induced on epithelial and tumor cells via stress or structural damage, including MICA, MICB and UL16-binding proteins (ULBPs), are recognized by NKG2D on both intraepithelial Vδ1 and circulating Vδ2 cells." (PMID 38274800, 2023). "Gamma delta T cells can respond to stress-induced molecules on tumour cells such as MHC class I polypeptide-related sequence A (MICA)." (PMID 38567060, 2023). "Because neoplasms are able to release NKG2D ligands MICA/B and ULBP1/2/3 by proteolytic cleavage, and thus evade NKG2D-mediated NK cell cytotoxicity." (PMID 36980527, 2023). "In normal conditions, NK cells are activated by the interaction between the receptor natural killer group 2 member D (NKG2D) and the tumour cell-expressed ligand MHC Class I-related chain A (MICA), which induces apoptosis." (PMID 37444377, 2023). "The cytotoxic effect of NK cells is reduced in the presence of soluble MICA and tumor cell–expressed HLA class I molecules." (PMID 38239881, 2023). "For example, the top five ncRNAs were miR-20a, miR-106b, miR-93, miR-155 and miR-372, indicating that different tumours mediate the role of MICA/NKG2D in immunoregulation through the same specific miRNA." (PMID 37784183, 2023). "For that end, many strategies that inhibit MICA shedding have been developed, which resulted in maintenance of tumour recognition and arrest of tumour progression." (PMID 37022605, 2023). "The miR-25-93-106b cluster can regulate tumour progression and invasion by regulating MICA expression, while tumours are sensitive to NK cells." (PMID 37784183, 2023).